ESRP1 (epithelial splicing regulatory protein 1)
Diseases named in the same sentence as ESRP1 in open-access papers (continued):
Sharing a sentence is not in itself a finding about the gene and the disease.
breast cancer (continued). "These contrasting results for ESRP1 in breast cancer may be partly attributed to the different subtypes or stages of breast cancer used in the studies." (PMID 38110955, 2023). "This was found to be due to hypoxia-driven reduced activity of tet methylcytosine dioxygenase 3 and increased activity of de novo DNA methyltransferases (DNMT3A and 3B), suggesting that oxygen-dependent epigenetic modifications is crucial in the regulation of ESRP1 expression in breast cancer." (PMID 38110955, 2023). "Hypoxic-induced exosomal delivery of TGF-β contributes to the elevation of TGF-β signaling, resulting in the regulation of human MENA alternative splicing and promoting EMT in breast cancer via the TGF-β-RBFOX2 (RNA binding Fox-1 homolog 2)-ESRP1 (epithelial splicing regulatory protein 1) axis." (PMID 36233088, 2022). "In addition, overexpression of ESRP1 and ESRP2 in basal-like breast cancer cells resulted in upregulation of E-cadherin expression, while in an ER-negative breast cancer model (MDA-MB-231 cells), low ESRP1 expression was associated with the development of EMT." (PMID 36052258, 2022). "In addition, HnRNP M can promote the expression of mesenchymal-specific CD44v through competitive interaction with ESRP1, thereby promoting breast cancer metastasis." (PMID 36052258, 2022). "The epithelial splicing regulatory protein 1 could form the basis for the prevention of Tamoxifen resistance in this breast cancer." (PMID 34356101, 2021). "Moreover, enforced E2F1 expression also increased the endogenous ESRP1 expression in breast cancer cell lines." (PMID 34362878, 2021). "Moreover, the association of reduced ESRP1 level with EMT acquisition and invasion is reported in multiple cancer types, including breast cancer." (PMID 34362878, 2021). "Clinically, in breast cancer, the expression of ESRP1 is positively correlated with circANKS1B." (PMID 34439339, 2021). "Furthermore, we also observed that the knockdown of SLUG under hypoxic conditions leads to the reduced invasion of breast cancer cells, which was reversed by both overexpression of hMENAΔ11a isoform and ESRP1 knockdown in the SLUG-depleted cells." (PMID 33089214, 2020). "Moreover, we found that circANKS1B biogenesis in breast cancer was promoted by splicing factor ESRP1, whose expression was also regulated by USF1." (PMID 30454010, 2018). "These suggest that ESRP1 is also a direct transcriptional target of USF1 in breast cancer." (PMID 30454010, 2018). "In breast cancer stem cells, ESRP1 is responsible for regulating ITGA6 splicing." (PMID 29401653, 2018). "ESRP1 negatively regulates EMT by preventing CD44 isoforms switch in breast cancer cells." (PMID 29747682, 2018). "Overall, our data identify a subset of metastatic breast CSCs characterized by CD44v expression, and suggest that CD44v and ESRP1 might be better prognosis markers and therapeutic targets for breast cancer metastasis." (PMID 28300837, 2017). "During EMT, ESRP1 levels drastically decrease, leading to the upregulation of the standard isoform (CD44s), which contributes to the formation of EMT-associated recurrent breast cancer in mice." (PMID 26273627, 2015). "Moreover, circANKS1B biogenesis in breast cancer is promoted by ESRP1." (PMID 39550559, 2024). "Hypoxia-induced TGF-β signaling upregulates SLUG and RBFOX2, which in turn transcriptionally repress ESRP1 expression; furthermore, ESRP1 downregulation promotes the generation of the hMENAΔ11a isoform, which results in the mesenchymal phenotype and thereby promotes breast cancer cell invasion." (PMID 38110955, 2023). "In particular, in public database analysis using BreastMark and TCGA data, ESRP1 expression was significantly associated with shorter overall survival in ER-positive, but not ER-negative, breast cancer, indicating the subtype-specific prognostic significance of ESRP1 expression." (PMID 38110955, 2023).
breast cancer (continued). "Furthermore, to investigate whether E2F1 follows a similar expression pattern in breast cancer as ESRP1, we analyzed TCGA database and observed that E2F1 is significantly upregulated in primary tumors compared to normal tissues." (PMID 34362878, 2021). "In addition, ESRP1 can affect drug resistance in breast cancer and colon cancer." (PMID 33495408, 2021). "Interestingly, a switch between RBFOX2 (also called RBM9) and ESRP1/2 splicing factors has been involved in epithelial to mesenchymal transition (EMT), and EMT was previously found associated with Doxo resistance in breast cancer." (PMID 31943118, 2020). "Interestingly, ZEB1 directly represses the ESRP1 locus in breast cancer cells." (PMID 32005677, 2020). "Notably, knockdown of ESRP1 also inhibited breast cancer invasion and the effect could be largely rescued by circANKS1B overexpression, as showed by transwell invasion assay." (PMID 30454010, 2018). "However, ESRP1 may also promote lung metastasis of orthotopically transplanted breast cancer cells by generating CD44 isoforms independently of EMT." (PMID 28975893, 2017). "Therefore, an in-depth exploration of the mechanism of action of ESRP1 in breast cancer and the development of targeted therapeutic drugs against ESRP1 are expected to provide new perspectives and strategies for the diagnosis, treatment, and prognosis of breast cancer." (PMID 40046628, 2025). "The TF SPI1 and the RBPs ESRP1, ESRP2 and PCBP1 featured frequently in detected statistical interactions, suggesting additional mechanistic roles for these proteins in breast cancer." (PMID 38838009, 2024). "SLUG knockdown caused an increase in ESRP1 expression, and TGF-β-induced SLUG upregulation led to the transcriptional downregulation of ESRP1 in breast cancer cells, indicating that SLUG acts as a transcriptional repressor of ESRP1." (PMID 38110955, 2023). "RBFOX2 transcriptionally represses ESRP1, and the ratio of ESRP1 and RBFOX2 determines the alternative splicing of hMENA in breast cancer." (PMID 38110955, 2023). "In the study we found that, similar to the basal-like subtype of breast cancer, OSCC cells with high levels of ZEB1/2 and low levels of E-cadherin and ESRP1/2 exhibited mesenchymal-like traits with FGFR(IIIc) isoforms." (PMID 31682640, 2019). "By contrast, OSCC cells with low levels of ZEB1/2, and high levels of E-cadherin and ESRP1/2 exhibited epithelial-like traits with FGFR(IIIb) isoforms, similar to the luminal-like subtype of breast cancer." (PMID 31682640, 2019). "The expression of both ESRP1 and ESRP2 is differentially regulated by cell density and hypoxia in breast cancer cells, suggesting local and microenvironmental control of p120 isoform expression." (PMID 31569498, 2019). "In breast cancer, cells with high levels of ZEB1/2 and low levels of ESRP1/2 and E-cadherin are categorized into the “basal-like” subtype of breast cancer with aggressive behavior and poor prognosis." (PMID 31682640, 2019). "Mercurio and colleagues show, in breast cancer, that α6B is positively controlled by autocrine VEGF-A signalling that culminates in transcriptional repression of the RNA-splicing factor ESRP-1." (PMID 31463571, 2019). "Snail-mediated ESRP1 repression results in a decrease in the levels of CD44v and an increase in production of the CD44s isoform, which drives EMT in breast cancer cells." (PMID 29747682, 2018). "Epithelial splicing regulatory proteins (ESRP1 and ESRP2) have been shown to regulate epithelial cell-type-specific splicing, including CD44v / CD44s switching regulated by ESRP1 in breast cancer cells." (PMID 29415026, 2018). "Higher levels of ESRP1, as well as higher ratios of ESRP1/ZEB1 and/or ESRP1/HAS2, canpredict poor survival in multiple breast cancer datasets." (PMID 31069317, 2018).
breast cancer (continued). "RBFOX2 plays a dual role in that it is both an important co-regulator of ESRP1 in epithelial phenotype cells and a mesenchymal-specific splicing factor during EMT and in more aggressive breast cancer subtype cell lines." (PMID 27911856, 2017). "Indeed, ESRP1-CD44v-xCT axis has been demonstrated to enhance the efficiency of breast cancer cells to form metastatic foci in the lungs; CD44v-positive 4T1 murine breast cancer cells are significantly able to metastasize to the lungs as compared with CD44v-negative 4T1 cells." (PMID 28289330, 2017). "On the basis of these assumptions, we tested two ratios between the epithelial and mesenchymal specific splicing factors, ESRP1/RBFOX2 and ESRP2/RBFOX2 in an early breast cancer setting." (PMID 27911856, 2017). "In cell lines and primary breast cancer tissue, ZEB1 reduces the expression of Both RAB25 and ESRP1, which have tumor suppressor functions." (PMID 26646320, 2016). "ESRP1 was shown to regulate a switch in CD44 alternative splicing, an event required for EMT and breast cancer progression." (PMID 23887935, 2013). "have experimentally demonstrated that compared to non-breast cancer patients, the mRNA expression level of ESRP1 is significantly upregulated in breast cancer tissue samples, while the mRNA expression level of ESRP2 is not upregulated." (PMID 40046628, 2025). "In addition, there are reports of DNA methylation changes in ESRP1 in prostate cancer and of ESRP2 in breast cancer, and our examination of TCGA data demonstrated ESRP2 methylation changes in several other adult cancer types." (PMID 34520622, 2022). "In addition, the Kaplan–Meier survival analysis using the TCGA database revealed that breast cancer patients expressing high levels of E2F1 exhibit a poor prognosis, which is in harmony with ESRP1." (PMID 34362878, 2021). "Moreover, TET3 knocked-down cells under normoxia exhibited an identical alternative splicing pattern of ESRP1 targets (hMENA, SLK, SCRIB, RALGPS2, SLC37A2, FNIP1, CD44, and ARHGEF1) as the hypoxic breast cancer cells." (PMID 34362878, 2021). "In addition, evidence from experiments shows the interaction between ESRP1 and hnRNPM is related to EMT and breast cancer subtyping." (PMID 33976726, 2021). "Indeed ESRP1, by regulating the alternative splicing of its target, CD44, also promotes lung metastasis of 4T1 breast cancer cells as well as brain-metastatic progression of melanoma, with elevated ESRP1 expression negatively correlating with patient survival." (PMID 31963158, 2020). "Increased ESRP1 can enrich for CD44v; thus, consistent with the prognostic ability ofESRP1, higher levels of CD44v, but not high CD44s or total CD44 levels, areprognostic markers for distant metastases in lung and breast cancer." (PMID 31069317, 2018). "Recently, ESRP1 has been reported to act as a tumor suppressor by negatively regulating epithelial-to-mesenchymal transition (EMT) and the metastatic potential of human breast cancer cell lines, via the splicing of different isoforms of CD44 or EXO70." (PMID 28975893, 2017). "To identify a new early prognostic marker of metastasis, we evaluated EMT-related gene expression in breast cell lines, and in primary tumor tissue from 31 patients with early breast cancer, focusing our attention on EMT-related splicing factors ESRP1, ESRP2 and RBFOX2." (PMID 27911856, 2017). "The search for differences in gene expression that might contribute to PB resistance suggested a role for the ZEB1-RAB25/ESRP1 pathway, which is involved in epithelial-mesenchymal transition (EMT) and is known to affect chemoresistance in breast cancer." (PMID 26646320, 2016). "Epithelial splicing regulatory proteins 1 and 2 (ESRP1/2) control the splicing pattern during epithelial to mesenchymal transition (EMT) in a physiological context and in cancer, including breast cancer (BC)." (PMID 35887187, 2022).
breast cancer (continued). "However, overexpression of ESRP1 cannot induce a differential CD44V splicing pattern in breast cancer cells, which suggests that ESRP1 is not the major regulator of CD44V splicing." (PMID 36292918, 2022). "However, E2F1 fails to upregulate ESRP1 despite its abundance in oxygen-deprived breast cancer cells." (PMID 34362878, 2021). "In addition, breast cancer cells treated with 5-aza-2′-deoxycytidine (5-Aza-dc), an established DNA methylation inhibitor, reduced the methylation level of the E2F1 binding site, which, in turn, restored the E2F1 binding on the ESRP1 promoter." (PMID 34362878, 2021). "ESRP1 down-regulation is able to promote EMT in several solid cancers, such as pancreatic cancer and breast cancer, but further experiments will be necessary to clarify the conundrum of functions of miR-23a in inducing of pancreatic cancer cell EMT and metastasis by targeting ESRP1." (PMID 29137308, 2017). "Knockdown of ESRP1 activity in breast cancer cells restored the non-EMT-inducing isoform of CD44 and suppressed metastasis, evidence that ESRP1 acts as an oncogene." (PMID 28333948, 2017).
ovarian carcinoma (24 papers, 2016 to 2025). A malignant neoplasm originating from the surface ovarian epithelium. "Previous studies have found that ESRP1 is highly expressed in ovarian cancer associated with a shorter patient survival." (PMID 32467669, 2020). "Our study provides a new understanding of the underlying biology of ovarian cancer by which high ESRP1 could lead to aggressive colonization in EOC." (PMID 32467669, 2020). "Another study on ESRP1 in ovarian cancer showed that ESRP1 overexpression in tumor cells resulted in an immunosuppressive microenvironment." (PMID 38815867, 2024). "circ-NOLC1 bound to ESRP1, and circ-NOLC1 overexpression significantly increased the levels of ESRP1 protein and mRNA in ovarian cancer cells." (PMID 38110955, 2023). "circ-0005585 upregulated ESRP1 expression by sponging miR-23a/b and miR-15a/15b/16 in ovarian cancer cells." (PMID 38110955, 2023). "Conversely, forced ESRP1 expression in the mesenchymal states of breast or ovarian cancer cells induces a phenotypic switching from the mesenchymal to epithelial state." (PMID 38110955, 2023). "Switching from CD44 variant isoforms containing exon v7 to isoform 4 without change in a total amount of CD44 was observed in human epithelial ovarian cancer cell line HO8910 with a stable suppression of ESRP1 expression." (PMID 38106992, 2023). "Snail also was found to increase CD44s in ovarian cancer cells through directly binding to E-boxes in the ESRP1 (epithelial splicing regulatory protein 1) promoter." (PMID 35682836, 2022). "The overexpression of ESRP1 in ovarian cancer promotes the transformation of ovarian cancer cells from mesenchymal phenotype to epithelial phenotype." (PMID 34026613, 2021). "We demonstrated that circ-NOLC1 promotes ovarian cancer tumorigenesis and development by binding to ESRP1 and modulating CDK1 and RhoA levels." (PMID 33483472, 2021). "Recently, a panoply of research has established the elevated ESRP1 level as a significant determinant of tumorigenesis in several cancers, such as colorectal cancer, ovarian cancer, and head and neck cancer." (PMID 34362878, 2021). "ESRP1 is also upregulated in primary ovarian cancer than normal ovarian tissues and promotes cell proliferation and colonization, which is associated with poor patient outcome." (PMID 34362878, 2021). "A series of recent studies have established an elevated ESRP1 level as a key determinant of tumorigenesis in several cancers, such as colorectal cancer, ovarian cancer, and head and neck cancer." (PMID 34362878, 2021). "We found that overexpression of ESRP1 inhibited migration and invasion and promoted colony formation of ovarian cancer cells." (PMID 32467669, 2020). "Our recent paper found that ESRP1 was highly expressed in ovarian cancer compared to normal or benign ovarian tissue." (PMID 32467669, 2020). "The results indicated that ESRP1 had a significant role in promoting the development of ovarian cancer in vivo." (PMID 32467669, 2020). "In order to find the molecular mechanism that leading to high expression of ESRP1 in ovarian cancer cells, we determined that circ-0005585 increased ESRP1 by competitively binding to miR-23a/b and miR-15a/15b/16." (PMID 32467669, 2020). "To clarify the carcinogenic effect of ESRP1 in ovarian cancer, we found that ESRP1 inhibited cancer cell migration and invasion by alternatively splicing cytoskeleton-associated proteins Rac1 and EPB41L5, and promoted colonization and colony formation." (PMID 32467669, 2020). "And further studies are needed to elucidate the specific functions and mechanisms of ESRP1 on malignant biological behavior of ovarian cancer." (PMID 32467669, 2020). "However, ESRP1 has been found to promote cancer progression in some cancers, such as breast and ovarian cancers, indicating that it plays a dual role in cancer progression depending on the type of cancer." (PMID 38110955, 2023). "ESRP1 has been shown to play a pro-tumorigenic role in ovarian cancer." (PMID 38110955, 2023).